IL10 (interleukin 10)
Diseases named in the same sentence as IL10 in open-access papers (continued):
Sharing a sentence is not in itself a finding about the gene and the disease.
melanoma (continued). "The IL‐10 loaded LNPs enhanced the proliferation and cytotoxicity of T cells and improved the antitumor effect of adoptive transferred OT‐1 CD8+ T cells to melanoma." (PMID 40056044, 2025). "Deep phenotypic analysis of circulating B cells from patients and HV demonstrated increased frequencies of DN B cells alongside IL-10+CD95+ plasmablasts, and concurrent collapse in memory B cell subsets in melanoma." (PMID 40449958, 2025). "This research emphasizes the importance of high levels of IFN-γ and low levels of IL-10, or a higher ratio of IFN-γ to IL-10, in mounting an effective protective response against murine B16F10 melanoma." (PMID 41019059, 2025). "IL-10 has been shown to be immunosuppressive in several tumor models and promoting tumor survival, notably in the B16F10 melanoma model." (PMID 39841829, 2025). "This study seeks to address these gaps by providing real-world longitudinal data on serum TNF-α, IL-2, and IL-10 dynamics in a cohort of patients with stage IV NSCLC and melanoma undergoing anti-PD-1 therapy with Nivolumab." (PMID 41020868, 2025). "Treatment with an IL-10 fusion protein (IL-10-Fc) has been evaluated in murine models of colorectal (CT26) and melanoma (YUMM1.7-OVA) tumors." (PMID 39941865, 2025). "These included Il10, Ccl2, and Cxcl2, which are also up-regulated in response to SHP2 inhibition in melanoma." (PMID 40992926, 2025). "IL-10 and IDO similarly lessen the responses of NK cells, CD4+ and CD8+ lymphocytes against melanoma." (PMID 38426087, 2024). "Serum IL-1β, IL-4, IL-6, IL-10, GM-CSF, TNF-ɑ, and sPD-L1 had a significant sex-related predictive impact on ORR, PFS and OS in melanoma and NSCLC patients treated with ICIs." (PMID 38443899, 2024). "For example, serum IL-1β, IL-4, IL-6, IL-10, GM-CSF, TNF-α, and sPD-L1 has significant sex-related predictive effects on OS in patients with melanoma or non-small cell lung cancer treated with ICIs." (PMID 39085893, 2024). "For example, increase of IL-10+ Bregs isolated from melanoma patients pre-treatment, positively correlated with a lack of response to anti-CTLA-4 treatment, indicating the potential to utilize IL-10+ Bregs as a biomarker for treatment response." (PMID 39346706, 2024). "Sun and colleagues demonstrated that STAT3, activated by IL-10 released in the TME, enhances the anti-tumoral activities of CTLs and promotes their differentiation in mouse models of melanoma." (PMID 39281678, 2024). "The authors have identified that tumor-infiltrating B-1a cells promote melanoma growth by suppressing the production of IFN-γ and TNF-α by CD8+ T cells through an IL-10-dependent mechanism." (PMID 38629061, 2024). "Melanoma tumor cells secrete local immune-suppressing chemicals known as transforming growth factor beta (TGF-ß) and IL-10." (PMID 39273452, 2024). "To further support this data, we tested the production of IL-10 and TGF-β, as well-known immunosuppressive cytokines in melanoma microenvironment, by melanoma cell lines." (PMID 38239354, 2023). "In the hypoxic TME of melanoma, tumor cells accumulate HIF-1 and also release high mobility group box 1(HMGB-1), which induces macrophages to produce IL-10 driving them to an M2-like phenotype that promotes proliferation and metastasis." (PMID 36816959, 2023). "In contrast, inhibiting STAT3 by specific inhibitors or STAT3 siRNA decreases the levels of IL-6, IL-10, and VEGF mRNA expression in melanoma cells." (PMID 36979654, 2023). "TGF-β1 and IL-10 are major tumor-supporting cytokines in the TME of many cancers, including malignant melanoma, which have similar functions and are working together in a positive feedback loop to restrict immune responses." (PMID 37501121, 2023). "According to a previous study, melanoma cells transduced with SNAIL showed typical EMT characteristics accompanied by increased mRNA expression of transforming growth factor-β (TGF-β), IL-10, and TSP1." (PMID 35595735, 2022).
melanoma (continued). "IHC/IF analyses of melanoma lesions identified substantial populations of TGF-β-expressing and TNF-α-expressing CD20+ TIL-B in melanoma lesions, while the presence of IL-10+ TIL-B was less frequent." (PMID 35909944, 2022). "Triptolide inhibited melanoma growth by reducing Foxp3 mRNA levels in the spleen and auxiliary lymph nodes, as well as TGF-β, IL-10, VEGF and Tregs within the TME." (PMID 36700235, 2022). "A previous phase II trial with nivolumab in melanoma cases has shown that IFN‐γ, IL‐6, and IL‐10 levels in the responders were significantly increased when compared to non-responders (p < 0.0001, p = 0.0007, and p < 0.0001, respectively)." (PMID 35992783, 2022). "TIE-2+ M-MDSC from melanoma patients overexpressed immune suppressive molecules such as PD-L1, CD73, TGF-β, and IL-10, suggesting a highly immunosuppressive phenotype." (PMID 35935946, 2022). "Another intriguing pathway, the interleukin 10 (IL-10) signaling pathway, reported in PAGER also shows how literature supports its involvement in melanoma." (PMID 35495152, 2022). "Other studies on SNPs in melanoma genes demonstrated that various cytokines (TNF-a, IL-6, IL-10, IFN-c, and TGF-b1) are involved in melanoma progression and immune escape." (PMID 35334544, 2022). "The levels of IL-6, IL-8, IL-10, IL-17A, IL-27, IL-31, GM-CSF, IFN-α, IL-9, VEGF-D, TNF-β, NGFβ, IL-23, IL-22, and IL-1α were below the threshold of detection in both melanoma patients and healthy controls." (PMID 33574842, 2021). "In melanomas, activation of Wnt/β-catenin signaling also reportedly led to the upregulation of IL-10 through the binding of β-catenin/T-cell factor (TCF) on the IL-10 promoter, thereby contributing to the formation of an immunosuppressive environment." (PMID 34359568, 2021). "Like melanoma, pDCs exposed to liver tumor-derived factors increased the expression levels of ICOSL to promote Tregs to produce increased IL-10, thereby strongly inhibiting T cell responses and ultimately assisting immunosuppression and tumor progression." (PMID 34737750, 2021). "Inhibition of BRAF/MEK signaling by silencer (si)RNA and pharmacological inhibition decreased the production of pro-tumorigenic factors such as IL-1α/β, IL-6, IL-8, IL-10, and VEGF by melanoma cells." (PMID 34576054, 2021). "Thus, LTA and IL-10 are not expressed in a distinct population, but in all analyzed B cell subpopulations and metastasis of primary melanoma is associated with a decrease in LTA+ memory-like and, to a minor degree, in LTA+ activated B cells but not in IL-10+ B cell subpopulations." (PMID 34359321, 2021). "Secondly, ACT of OT-I CD8+ T cells with IL-10-Fc led to potent tumour regression in a large and established YUMM1.7-OVA melanoma model." (PMID 34621543, 2021). "The interplay between melanoma and stromal cells in the TME, including DCs, is mainly supported by presence of IL-6, IL-10, and VEGF." (PMID 33467521, 2021). "Treg cells can recognize specific melanoma markers gp100 and TRP-1, produce IL-10 and inhibit anti-tumor response of T lymphocytes CD4+CD25−." (PMID 33287312, 2020). "Previous research reports that melanoma cells express ICOS ligand to promote the activation and expansion of T regulatory cells and enhance the IL-10 production of Treg cells." (PMID 31998801, 2020). "Thus, IL-10 blockade in the metastatic melanoma environment may normalize DC development and allow for development and/or attraction of inflammatory non-classical monocytes, effectively facilitating immune checkpoint blockade by anti-PD1 and anti-CTLA4/ipilimumab, respectively." (PMID 32507967, 2020). "Melanoma cells produce immunosuppressive cytokines, such as PGE2, IL-10 and TGF-β, that can inhibit TLR7/9 and IRF7 expression leading to a limited I-IFN production by pDCs." (PMID 32054102, 2020). "Melanoma cell-derived immunosuppressive cytokines TGF-β and IL-10 play a crucially important role in the process of tumor initiation." (PMID 32695181, 2020).
melanoma (continued). "For example, serum baseline IL-8 levels reflected and predicted response to anti-PD-1 treatment in patients with melanoma and NSCLC, while baseline IL-10 correlated with tumor relapse in melanoma." (PMID 31775882, 2019). "Next, in vitro generated TAM from SK- BR- 3 TCM and the cytokines IL-4, IL-10, and M-CSF were compared to TAM derived from melanoma tumor tissue using the same flow panel and gating strategy." (PMID 31138333, 2019). "In detail, melanoma cells which overexpress STAT3 protein inhibit the expression of proinflammatory cytokines and chemokines, such as VEGF, IL-10, and IL-6." (PMID 31569642, 2019). "Based on these observations, we analyzed the ratio between the levels of IL-10 and the other cytokines (IL-6 and CXCL1) in the melanoma microenvironment." (PMID 31374840, 2019). "IL-1α, IL-10, TGF-β, IL-8, and IL-4 mRNA were all upregulated during melanoma progression with a significant increase in metastatic compared to primary human melanomas suggesting transcriptional regulation." (PMID 30712866, 2019). "In uninfected melanoma cells, increasing numbers of Tregs with corresponding increases in TGF-ß and IL-10 release were detected." (PMID 31192129, 2019). "Llopiz and co-workers showed that the application of anti-IL-10 monotherapy did not cause the expected therapeutic results, but its application with adjuvants, was capable of inducing the activation of DCs, which can potentially lead to complete B16 melanoma tumor rejection." (PMID 29954431, 2018). "Melanoma can produce immunosuppressive cytokines, such as TGF-β, VEGF and IL-10, to create an immunosuppressive microenvironment that facilitates tumor growth and blocks antitumor immune responses." (PMID 29301578, 2018). "This is in-line with our finding that melanoma-conditioned TAMs displayed M2-like phenotype, including increased CD163 protein expression and TNF-α low, IL-1β low, TGF-β high and IL-10 high phenotype." (PMID 30459241, 2018). "To determine how these CD4+Foxp3+IL-10+ cells affect the anti-metastatic effects of metformin, we injected C57BL/6J mice with anti-CD25 1 day prior, and 1 and 7 days after B16F10 melanoma inoculation." (PMID 29899823, 2018). "The identified inversion between IL-10 and VEGF levels in melanoma patients requires further investigation." (PMID 29849947, 2018). "A lot of researchers have reported about the imbalance of cytokines in patients with melanoma - statistically low levels of IL-2 and IFN-γ and high levels of IL-4, IL-6 and IL-10 that reflects the imbalance between Th1/Th2 immune responses." (PMID 29849947, 2018). "Differentiation of IL-10-producing regulatory DC has also been shown to be driven by autocrine IL-6/IL-10 signaling through STAT3 in DC, which is initiated by melanoma-derived factors that activate the TLR2 signaling pathway in these cells." (PMID 29209327, 2017). "As shown with melanoma, mRNA levels of IFN-γ, TNF-α, IL-2, IL-18, IL-10, and VEGF-A were significantly decreased in kCYC mice compared with WT mice in draining LNs on day 14 (p < 0.05, respectively)." (PMID 26098776, 2015). "The mRNA content of IL-10 and its receptor subunits (IL-10Rα and IL-10Rβ) was analyzed by quantitative PCR (qPCR) in two cutaneous (G361 and GR-M) and one uveal (OCM-1) melanoma cell lines and compared to that of NHEM." (PMID 26631117, 2015). "In the same series of tumors, stronger IL-27 staining was found in advanced thick melanomas and correlated with PDL-1 and IL-10 expression." (PMID 26218530, 2015). "Our data demonstrates there was increased amount of T CD8 IL-10+ lymphocytes and IFNγ MIF when mice with melanoma were treated with BMDCs stimulated with GK-1 and loaded with MAGE-AX." (PMID 25759825, 2014). "Since presence of both IL-10 and IL-10-secreting Treg was demonstrated in B16F10 melanoma [our data and 24], we explored the possibility to counteract the effects of intratumoral IL-10 to unleash protective effector responses." (PMID 23663506, 2013).
melanoma (continued). "Serum cytokine levels (including IL-1α, IL-1β, IL-2, IL-6, IL-10, IL-12, TNF-α, IFN-γ and IFN-α) were lower in A375 melanoma bearing mice treated with G3139 + VRP + ACV + PAC.PBP + DNR + X rays than in controls treated with physiological saline." (PMID 22233801, 2012). "The pleiotropic cytokine TGFβ1 increases the expression of IL-10 and MCP-1 in melanoma cells, through a crosstalk between Smad, PI3K/AKT, and BRAF-MAPK signaling pathways." (PMID 22046194, 2011). "The general trend observed in consecutive stages of melanoma was a gradual build up of the immunosuppressive markers ILT3, FOXp3, IL-10 and IDO, with peak expression occurring in positive SLN." (PMID 17565341, 2007). "As with ILT3 and FOXp3, expression of both IL-10 and IDO increased with melanoma progression from skin into the lymph nodes, the peak occurring in positive SLN." (PMID 17565341, 2007). "Moreover, LPA is a potent regulator of IL-10 gene transcription and protein release via DR6, resulting in decreased HLA-DR expression in melanoma cells." (PMID 39187677, 2025). "Based on 435 melanoma samples, LPAR1 expression strongly correlated with the expression of NF-κB1 (Spearman’s r = 0.23, P = 9.8 × 10−7), DR6 (Spearman’s r = 0.33, P = 1.9 × 10−12) and IL-10 (Spearman’s r = 0.21, P = 1.3 × 10−5)." (PMID 39187677, 2025). "While cancer type did not significantly affect IL-10 concentrations, melanoma cases exhibited a more pronounced upward trajectory in early measurements." (PMID 41020868, 2025). "Compared to primary melanoma lesions, lymph node metastases have been demonstrated to have higher levels of indoleamine 2,3-dioxygenase (IDO), interleukin (IL)-10, regulatory T cells, and tolerogenic dendritic cells, which have the combined effect of creating an immunotolerant environment." (PMID 41148835, 2025). "On the contrary, T2-MZP cells accumulated in tumor-draining lymph nodes and promoted tumor (B16-F10 melanoma) growth, but did not increase IL-10 levels; therefore, IL-10 is likely not an exclusive regulatory mechanism utilized by this subset." (PMID 41346623, 2025). "IL-10 can inhibit essential steps in immune detection by decreasing the cell surface expression of HLA class I and II antigens and the intercellular adhesion molecule-1 (ICAM-1) in melanoma cells." (PMID 39187677, 2025). "Distinct patterns of immune activation and regulation are evident between cancer types, with melanoma patients generally exhibiting stronger pro-inflammatory responses (e.g., IL-2 and TNF-α elevations), while IL-10 dynamics suggest differential regulatory feedback." (PMID 41020868, 2025). "However, melanoma cells within the TME secrete IL-6, IL-10, VEGF, and TGF-β, which disrupt DC recruitment and maturation, thereby impairing T-cell activation and promoting melanoma progression." (PMID 40936894, 2025). "Since IL-10 plays a crucial role in the progression of melanoma, we investigated whether LPA could regulate IL-10 expression." (PMID 39187677, 2025). "Melanoma-derived soluble factors and metabolites, such as TGF-β, IL-10, IL-4, and IL-13 May contribute to this shift toward acquisition of pro-tumorigenic features." (PMID 38533720, 2024). "Furthermore, we show that IFNγ stimulated dedifferentiated melanoma cells display increased secretion of CCL2, IL-10, CXCL10 and PD-L1 and increased PD-L1 expression on their cell membranes." (PMID 39736644, 2024). "PAF also promotes the production of immunosuppressive cytokines such as IL-10 and TGF-β while inhibiting the release of pro-inflammatory cytokines such as TNFα and interferon-gamma, allowing melanoma cells to evade immune surveillance and promoting tumor progression." (PMID 38791873, 2024). "In hypoxic environments, melanoma cells have been reported to enhance release of the DAMP High-Mobility Group Box 1 protein (HMGB1), driving accumulation of M2-like macrophages at the tumor site and release of IL-10." (PMID 38533720, 2024).
melanoma (continued). "MDSCs secrete TGF-β and IL-10, which inhibit effector T cell function, and they may enhance FOXP3+ Treg formation in malignancies like melanoma by releasing IL-10 and IFN-γ, according to multiple studies." (PMID 37795038, 2023). "In melanoma, elevated level of TGF-β was reported to activate PI3K/AKT signaling and promote the tumor infiltration of immune-suppressive monocytes by upregulating monocyte chemoattractant protein-1 (MCP-1) expression and IL-10." (PMID 37740232, 2023). "Additionally, a rise in other cytokines, including IFN-α, IFN-γ, IL-10, CCL3, and CXCL10, was seen in both melanoma-treated groups receiving LIVP-RFP or LIVP-FlaB-RFP." (PMID 37112810, 2023). "In this respect, by inhibiting IL-10 production, CD200 tumoral expression may serve a favorable role in melanoma by facilitating the transition of TAMCs to the M1 phenotype." (PMID 38137547, 2023). "Thus, IL-6, IL-10, and TNF-α have been significantly decreased, inhibiting the growth and migration of melanoma cells, suggesting the potential of the two compounds tested to be used as antitumor drugs targeting inflammatory cytokines." (PMID 36829966, 2023). "Here, we showed that EVs from the metastatic melanoma cells inhibit the release by keratinocytes of the IL6, IL8, IL10, and IL12 immunomodulatory cytokines and the regulators of cell adhesion and immune cell infiltration, such as sICAM-1, s-ICAM-3, sPECAM-1, sE- and sP-selectins, t-PA, and sCD40L." (PMID 35327461, 2022). "Moreover, EVs reduced the production of different cytokines (IL6, IL10, and IL12) and adhesion factors (sICAM-1, sICAM-3, sPecam-1, and sCD40L) usually secreted by keratinocytes to control melanoma progression." (PMID 35327461, 2022). "Melanoma disease progression shows distinct dynamics of functional B cell subpopulations, with the regulation of LTA+ B cell numbers being more significant than IL-10+ B cell subpopulations." (PMID 34359321, 2021). "Therefore, we compared primary human melanomas and melanoma metastases for the composition of LTA+ and IL-10+ B cell subpopulations." (PMID 34359321, 2021). "In addition, β-catenin-overexpressed by melanomas inhibits the production of IFN-γ by melanoma-specific cytotoxic lymphocytes, in an IL-10-independent manner." (PMID 33407613, 2021). "Moreover, we observed a slight rise in the secretion of IL-10 and TGF-β with anti-PD-1 therapy in vivo compared to control melanoma mice, implying an enhanced immune suppression." (PMID 33936081, 2021). "Another study performed by Schrama’s group showed that as melanoma progressed in these melanoma-prone mice, there was an increase in Tregs, a decrease in CD8+ T cells within tumor tissues, and an increase in immunosuppressive cytokines, IL-10 and TGF-β." (PMID 33256089, 2020). "The replacement of IL-10 to the human cell line of melanoma A375P, which does not produce endogenous IL-10, using a vector containing the murine IL-10 cDNA, reversed tumor growth and lung metastasis." (PMID 32283655, 2020). "We also assessed expression of activation-responsive immune genes TNF, IL21, IL10, IL13, and CFS2 in the ICB melanoma dataset, and found that IFNG, TNF, and interleukins IL21 and IL10 seemed to increase upon treatment in responders, even though they were not differentially expressed." (PMID 32471032, 2020). "Interestingly, inflammatory cytokines including IL-6, IL-10, IL-12p70, IFN-γ, TNF-α, MCP-1 and KC were previously shown to be differentially expressed in male and female C57 BL/6J mice in the melanoma model." (PMID 33287312, 2020). "Both IFN-γ/IL-10 mRNA ratio and CD4 + subpopulations ratio in PBMCs could predict response to anti-PD-1 in immunotherapy-naive melanoma patients." (PMID 33077770, 2020). "To date, there have been no investigations into the role of IL-10-producing B cells in patients with melanoma." (PMID 33569063, 2020).